PALB2 (partner and localizer of BRCA2)
Diseases named in the same sentence as PALB2 in open-access papers (continued):
Sharing a sentence is not in itself a finding about the gene and the disease.
hereditary cancer (20 papers, 2014 to 2026). Malignant neoplasms occurring in families at a rate greater than that expected by chance and caused by germline mutations in a specific gene. "We screened out 28 germline PALB2-mutation carriers among 480 familial cancer patients (including 143 FBC patients) in Geneplus database pool." (PMID 33193564, 2020). "Skaro et al27 reported that deleterious germline variations of hereditary cancer genes (eg, ATM, BRCA2, PALB2) were found in patients with IPMN associated with concurrent invasive cancer." (PMID 35171259, 2022). "To examine the clinical feasibility of the RAD51 assay, we scored archival breast tumor samples, including PALB2‐related hereditary cancers." (PMID 30377213, 2018). "We identified deleterious heterozygous germline mutations in well-established familial cancer-associated genes, BRCA2, PALB2, ATM and MLH1, in 14.5% (8/54) of our FPC patients." (PMID 27732944, 2016). "Previous studies in hereditary cancer settings have established that CNVs account for around 7–10% of all pathogenic variants (PVs) and are not limited to BRCA1 and BRCA2 but also occur in other high or moderate risk genes, like PALB2, ATM, CHEK2, and RAD51C." (PMID 41488399, 2026). "Among these, CHEK2 and PALB2, two of the genes involved in the homologous recombination pathway, have been associated with an increased risk of breast and other cancers, and are included in the NCCN guidelines for hereditary cancer risk assessment." (PMID 35456488, 2022). "In our analysis one of the BRCA1, BRCA2, RAD51C, and PALB2 mutations was found in 25.8% of familial cancer cases and in 9.9% of non-familial cases, similar to what has been reported previously." (PMID 33670479, 2021). "While all 18 PALB2-associated patients with familial cancers other than FBCs had additional somatic mutations, four of the 10 PALB2-associated patients with familial breast cancer had no additional somatic or germline mutations." (PMID 33193564, 2020).
breast tumors (18 papers, 2007 to 2025). "In our retrospective analyses of human breast tumors with BRCA1/2 or PALB2 mutations from patients, we observed a strong association between FLT1 activation in human tumor cells at pre-treatment and subsequent development of PARPi resistance." (PMID 38956205, 2024). "In this regard, the work was aimed to evaluate CNA and mutations of the BRCA1, BRCA2, and PALB2 genes in the breast tumor of patients and their predictive and prognostic potential." (PMID 37628606, 2023). "High expression of PALB2 was found in breast tumors and was significantly associated with enhanced aggressive phenotypes." (PMID 29321957, 2018). "Where possible, relatives of women found to carry PALB2 mutations were genotyped for the family-specific mutation, mutant transcripts were characterised and breast tumours arising in mutation carriers were recalled and reviewed." (PMID 23448497, 2013). "Thus, the aim of the work was to evaluate the predictive and prognostic potential of DNA copy number aberrations and mutations in the BRCA1, BRCA2, and PALB2 genes in breast tumors." (PMID 37628606, 2023). "Besides the mutational signature 3, the mutational signature R1 was also common in PALB2-associated breast tumors." (PMID 33193564, 2020). "Only four out of 28 tumors had true LOH at the PALB2 allele, including 2/10 breast tumors." (PMID 33193564, 2020). "Some information about the general morphology of breast tumors with PALB2 mutation is available." (PMID 26489409, 2015). "Indeed, the size distribution of deletions and the presence of a few other types of non-clustered rearrangements in RAD51C−/−, XRCC2−/−, XRCC3−/−, BRCA2−/−, or PALB2−/− mutant cells closely resembled the predominant rearrangement signature of BRCA2-deficient breast tumors." (PMID 31727117, 2019). "We confirmed the recently reported association of PALB2 PGVs with a tendency to the development of TNTs,22 accounting for 28% of breast tumors occurring in female PALB2 PGV heterozygotes known to our service." (PMID 34113003, 2021). "PALB2 PGVs are associated with grade 3, TN, and grade 3 ER-positive HER2-negative breast tumors." (PMID 34113003, 2021). "Mutational signature 3, which is related to defective HRR, was present in 4 of PALB2-associated breast tumors, including all three PALB2-NULL BC cases, but absent among sporadic breast tumors." (PMID 33193564, 2020). "Interestingly, a significant link was observed between PALB2 overexpression and tumors of histopathological grade III (P = 0.02), suggesting that overexpression of PALB2 plays a role in the aggressiveness of breast tumors." (PMID 29321957, 2018). "Similarly, PALB2 was found to be hypermethylated in 4/60 (6.7%) sporadic breast tumours and all four PALB2 methylated tumours also exhibit low PALB2 expression." (PMID 27666291, 2016). "In fact, nearly 40% of the PALB2-associated breast tumors identified to date displaied a triple-negative phenotype, regardless of the specific PALB2 mutation." (PMID 23935836, 2013). "Moreover, patients with BRCA1/2- or PALB2 (partner and localizer of BRCA2)-mutant breast tumors that display heightened FLT1 expression in their tumor cells at pre-treatment are at high risk for progression on PARPi." (PMID 38956205, 2024). "PALB2 BCs are not different from other breast tumors regardingcytokeratin 5/6 and 17 expression, but show higher expression of Ki-67 and lowercyclin D1 than other familial and sporadic BCs." (PMID 31067289, 2019). "The FA pathway has also been connected to TNBC, as comparison of mRNA expression in different breast tumor types revealed several FA pathway genes (BRCA1, FANCD2, FANCF, and PALB2) being significantly less expressed in TNBC tumors compared to luminal A (ER or PR positive) tumors." (PMID 28702895, 2017).
breast tumors (continued). "In comparison with breast tumours associated with other BC susceptibility genes, we thus confirm previous observations showing that ATM-associated tumours do not resemble BRCA1-associated tumours or PALB2-associated tumours, which are also predominantly triple-negative tumours." (PMID 29665859, 2018).
gastric cancer (18 papers, 2015 to 2024). A primary or metastatic malignant neoplasm involving the stomach. "We also found four pathogenic PALB2 mutations accompanied by either LOH or biallelic mutations in the TCGA gastric cancer cohort." (PMID 38589664, 2024). "For example, germline PALB2 variants have recently been associated with familial and sporadic stomach cancer." (PMID 34572800, 2021). "Our group, as a member of The Latin American Gastric Cancer Genetics Collaborative Group, recently described the role of germline mutations in homologous recombination pathway related genes such as PALB2, BRCA1, and RAD51C in patients with GC." (PMID 31600923, 2019). "Sporadic stomach cancers have been analysed as part of the TCGA study, and an association was identified between truncating PALB2 mutations and sporadic stomach adenocarcinoma." (PMID 29706558, 2018). "Stomach cancer has a relatively high rate of rare germline truncations, in large part due to frequent PALB2 and ATM mutations." (PMID 26689913, 2015). "We found that germline PALB2 variants were positively correlated with HRD in stomach cancers." (PMID 34572800, 2021). "Pathogenic variants in PALB2 and MRE11A were identified in a 34-year-old patient who was co-diagnosed with breast and gastric cancer." (PMID 29338689, 2018). "In the TCGA WES gastric cancer cohort, three BRCA2 deficient, four PALB2 deficient, two BRCA1 deficient and three BRCA1 promoter methylated cases all had an HRD score ≥42 (p < 1 × 10-5, Fisher exact test), which is the threshold for HR deficiency previously defined for ovarian cancer." (PMID 38589664, 2024). "The role of multiple PARP inhibitors has also been evaluated in gastric cancer (GC) conditions as mutated homologous DNA recombination genes such as BRC1/2, PALB2, ATM, RAD51C, and ARID1A carry somatic HRD." (PMID 35873570, 2022). "Mutations in homologous recombination (HR) repair genes, such as PALB2, likely explain a significant fraction of inherited gastric cancer (GC)." (PMID 35887173, 2022). "Among 40 females with BC and gastric cancer, 10 had PVs: BRCA2 (n = 3, 7.5%, 95% CI 2.0–21.5%) was the most frequent, followed by PALB2 (n = 2, 5.0%, 95% CI 0.9–18.2%) and CHEK2 (n = 2, 5.0%, 95% CI 0.9–18.2%)." (PMID 36856935, 2023). "Of the two individuals who carried two DV in genes other than MUTYH, one was affected with colorectal cancer and carried a DV in CHEK2 and PALB2, while the second was not personally affected with cancer but did have a family history of breast and gastric cancer and carried DV in PMS2 and CDH1 genes." (PMID 29308099, 2018).
invasive ductal carcinoma (16 papers, 2013 to 2025). "IMPC exhibited the highest mutation rate (4.26%) in PALB2, whereas the mutation rate in invasive ductal carcinoma was 0.73%." (PMID 38914840, 2024). "In summary, PALB2-associated tumours are mostly high histological grade invasive ductal carcinoma (11/15; 73%)." (PMID 23448497, 2013). "The mutation frequency of PALB2 in patients diagnosed with pure or mixed invasive micropapillary carcinoma was 4.26%, which was approximately 6-fold higher than that in patients diagnosed with invasive ductal carcinoma (0.73%)." (PMID 38914840, 2024). "For patients with invasive ductal carcinoma, the BRCA1/2 double mutation frequency was 1.35% (28/2079), and the BRCA1/2 and PALB2 triple mutation frequency was 0.91% (19/2079)." (PMID 38439896, 2024). "Another patient diagnosed at 36 years with invasive ductal carcinoma HR+, HER2-, had a PALB2 mutation c.1240C>T." (PMID 31658756, 2019). "The third carrier of PALB2:c.509_510del was diagnosed at 53 years with infiltrating ductal carcinoma." (PMID 29052111, 2018). "The proband that carried PALB2 c.2982_2983insT had a histological grade three, invasive ductal carcinoma diagnosed at age 45 years." (PMID 23448497, 2013). "Invasive ductal carcinoma accounted for 75% of all PALB2 carriers in our study." (PMID 38914840, 2024). "Therefore, patient 5 in the current series with a right breast invasive ductal carcinoma and a small bowel NET represents a novel clinical association with this PALB2 gene variant." (PMID 31592449, 2019). "The PALB2 truncating mutation c.1653T>A (p.Tyr551Stop) was identified in a woman diagnosed with an infiltrating ductal carcinoma (IDC), negative for estrogen receptor (ER), progesterone receptor (PR) and HER2 at the age of 36." (PMID 23935836, 2013). "This study provides novel insights into the subcellular distribution and potential interactions between PALB2 and IQGAP1 in human invasive ductal breast carcinoma, with a particular focus on the consequences of truncating PALB2 mutations." (PMID 40868059, 2025). "Future research should further explore how truncated PALB2 alters IQGAP1 function in cytoskeletal remodeling and proliferation dynamics, potentially driving tumor cell plasticity in invasive ductal carcinoma." (PMID 40868059, 2025). "Invasive ductal carcinoma was observed in 75% (9/12) of PALB2 carriers compared with 83.3% of the non-carriers." (PMID 38914840, 2024).
colorectal cancer (15 papers, 2007 to 2026). A primary or metastatic malignant neoplasm that affects the colon or rectum. "Identification of the variant chr16-23634870-TG-CA (PALB2: p.Gln559Ter) in an individual with a family history of colorectal cancer suggests that this genetic alteration predisposes individuals to the disease." (PMID 40869938, 2025). "Identifying new or rare genetic variants in genes such as PALB2 highlights the importance of investigating the role of new variants and predisposition genes in colorectal cancer." (PMID 40869938, 2025). "Early onset colorectal cancer patients from our study showed more frequently mutated NOTCH1 tumor suppressor and the DNA strand break repair gene PALB2, and mutations of these genes can be related to the early tumor initiation and generally worse prognosis from young colorectal cancer patients." (PMID 35003350, 2021). "The possibility that PALB2 predisposes to colorectal cancer is worthy of further investigation." (PMID 18053174, 2007). "Furthermore, elevated PALB2 expression was associated with poorer overall survival, suggesting that PALB2 expression levels may also serve as a novel prognostic factor for colorectal cancer patients, similar to MRE11." (PMID 37372450, 2023).
Wilms tumor (15 papers, 2012 to 2025). An embryonal neoplasm characterized by the presence of epithelial, mesenchymal, and blastema components. "The KT-10 Wilms tumor PDX model has a PALB2 mutation, hence is defective in homologous recombination and is sensitive to TLZ." (PMID 31921673, 2019). "WTX and PALB2 are both considered as tumor suppressor genes since their mutations are often found in kidney tumor (Wilms tumor) and breast and pancreatic cancers, respectively." (PMID 23272301, 2012). "Cases in group FA-D1 (mutated in BRCA2) and FA-N (mutated in PALB2) present with a distinct, relatively severe, phenotype that is characterized by the development of leukemia at very young age (median 2.2 years) and by pediatric cancers such as nephroblastoma (Wilms tumor) or medulloblastoma." (PMID 22778927, 2012). "Recent studies revealed that Wilms tumor gene on the X chromosome (WTX) and PALB2, a major BRCA2 binding partner known as FANCN, have been shown to interact with the DC domain of KEAP1, inhibit the ubiquitination of Nrf2 and promote NRF2-dependent transcription." (PMID 23272301, 2012).
lung carcinoma (14 papers, 2016 to 2025). "Three novel gene–cancer associations were found in this study, namely, PDE11A and PALB2 with lung cancer and SLX4 with liver cancer." (PMID 37610374, 2023). "While BRCA and PALB2 mutations have been recognized as predictive biomarkers in breast and ovarian cancers for some time, their role in gastrointestinal and lung cancers is evolving." (PMID 36964191, 2023). "In lung cancer, PALB2 mutations occurred at 1.8% of cases, which is the highest rate among all cancer types." (PMID 35087742, 2021). "Besides, five P/LP variants (one in ATM, two in BRCA2, and two in PALB2) were also found in 1117 lung cancer patients." (PMID 37930190, 2023). "Similarly, retrospective data suggest that BRCA and PALB2 mutations are associated with prolonged responses to platinum-based therapies in lung cancer, although this has yet to be validated in larger prospective studies." (PMID 36964191, 2023). "We identified several germline and somatic mutations (e.g., BRCA1/2, PALB2, ATM, and ATR mutations) associated with HRD phenotype in ovarian, breast, pancreatic, stomach, bladder, and lung cancer." (PMID 34572800, 2021). "We also identified independent missense associations for genes and phenotypes such as ENPEP and hypertension; GSDMB and asthma; IFIH1 and hypothyroidism; and PALB2 and lung cancer." (PMID 29691392, 2018). "Known lung cancer genes (EGFR, KRAS G12C, ALK, MET, RET) were found in 33 patients; 11 had genes relevant to both lung and other cancers (ERBB2, BRAF V600, NTRK), and 37 had genes typically linked to other malignancies (NF1, PIK3CA, PALB2, FGFR2B, FBX7, RAD51)." (PMID 40244261, 2025).
invasive breast carcinoma (13 papers, 2010 to 2025). A carcinoma that infiltrates the breast parenchyma. "In contrast, BRCA2 and PALB2-associated invasive breast cancers were more likely to be node-positive and were ER + HER2- in 63.2–70% of cases." (PMID 40275390, 2025). "This suggests that PALB2-mutation carriers are more likely to be diagnosed with invasive breast cancer than with DCIS." (PMID 40770660, 2025). "PALB2 mutations were detected in 0.2% of DCIS cases compared to 0.9% of invasive breast cancer cases." (PMID 40770660, 2025). "Women with invasive breast cancer from Jamaica and Barbados had high rates of PALB2 P/LP variants at 2.2% and 4.4%, respectively." (PMID 33646313, 2021). "In our study, women with invasive breast cancer from Jamaica and Barbados had high rates of PALB2 P/LP variants." (PMID 33646313, 2021). "The frequency of somatic PALB2 mutations among patients with invasive breast carcinoma in the TCGA database (TCGA-BRCA) was 1.12% (11/986)." (PMID 33193564, 2020). "Twenty-four invasive breast cancers from carriers of fourteen distinct pathogenic PALB2 germline mutations were included in this study." (PMID 31428676, 2019). "We screened 1,403 case probands for PALB2 mutations in a population-based study of Australian women with invasive breast cancer stratified by age at onset." (PMID 21182766, 2010). "RNASEL:p.Glu265* was identified in one of the PALB2 carriers who had two primary invasive breast cancer diagnoses before 50 years." (PMID 29422015, 2018). "One could posit that these invasive breast cancers may constitute non-PALB2-related cancers arising in the context of a PALB2 germline mutation." (PMID 31428676, 2019).